KLHDC2 (kelch domain containing 2)
Description:
Substrate-recognition component of a Cul2-RING (CRL2) E3 ubiquitin-protein ligase complex of the DesCEND (destruction via C-end degrons) pathway, which recognizes a C-degron located at the extreme C terminus of target proteins, leading to their ubiquitination and degradation. The C-degron recognized by the DesCEND pathway is usually a motif of less than ten residues and can be present in full-length proteins, truncated proteins or proteolytically cleaved forms. The CRL2(KLHDC2) complex specifically recognizes proteins with a diglycine (Gly-Gly) at the C-terminus, leading to their ubiquitination and degradation. The CRL2(KLHDC2) complex mediates ubiquitination and degradation of truncated SELENOK and SELENOS selenoproteins produced by failed UGA/Sec decoding, which end with a diglycine. The CRL2(KLHDC2) complex also recognizes proteolytically cleaved proteins ending with Gly-Gly, such as the N-terminal fragment of USP1, leading to their degradation. May also act as an indirect repressor of CREB3-mediated transcription by interfering with CREB3-DNA-binding.
Synonyms: HCLP-1; LCP; HCLP1
Tractability: Small molecule: a structure with a bound ligand is known. PROTAC: UniProt records ubiquitination sites on it; ubiquitination databases record sites on it.
Gene: Protein-coding gene on chromosome 14 (49,767,677 to 49,786,385, forward strand). Ensembl gene ENSG00000165516.
Subcellular location: Nucleus
Subcellular location (Human Protein Atlas): Nuclear membrane; Nucleoplasm; Nuclear bodies
Gene Ontology:
Molecular function: protein binding; ubiquitin-like ligase-substrate adaptor activity
Biological process: proteasome-mediated ubiquitin-dependent protein catabolic process; ubiquitin-dependent protein catabolic process via the C-end degron rule pathway; protein ubiquitination
Cellular component: Cul2-RING ubiquitin ligase complex; nuclear body; nuclear membrane; nucleoplasm; nucleus; cullin-RING ubiquitin ligase complex
Genetic constraint (gnomAD): Loss-of-function variants: 14 observed, 18.79 expected, observed/expected ratio (o/e) 0.74, 90% interval 0.49 to 1.16. The upper end of that interval is the gene's LOEUF score, 1.16, which puts it in group 5 of 6, group 1 being the genes least tolerant of losing a copy. Missense variants: 214 observed, 263.83 expected, observed/expected ratio (o/e) 0.81, 90% interval 0.73 to 0.91. Synonymous variants: 92 observed, 93.09 expected, observed/expected ratio (o/e) 0.99, 90% interval 0.83 to 1.17.
Homologues: Orthologues: chimpanzee KLHDC2 (100% identical), macaque KLHDC2 (99% identical), dog KLHDC2 (99% identical), rabbit KLHDC2 (98% identical), pig KLHDC2 (98% identical), mouse Klhdc2 (97% identical), rat Klhdc2 (89% identical), guinea pig KLHDC2 (84% identical), tropical clawed frog klhdc2 (68% identical), zebrafish klhdc2 (23% identical). Paralogues in human: KLHDC1 (41% identical), HCFC1 (24% identical), HCFC2 (23% identical), KLHDC4 (22% identical), KLHDC10 (21% identical), KLHDC3 (21% identical), RABEPK (19% identical), LZTR1 (18% identical), FBXO42 (17% identical), KLHDC9 (14% identical).
Diseases named in the same sentence as KLHDC2 in open-access papers:
KLHDC2 is named in the same sentence as 1 disease in open-access papers, as found by Europe PMC text mining. Sharing a sentence is not in itself a finding about the gene and the disease. The quoted sentences say what the papers report.
cancer (1 paper, 2025). A tumor composed of atypical neoplastic, often pleomorphic cells that invade other tissues. "As such, KLHDC2 is emerging as a novel powerful degrader, and the hope is that through the development of potent small molecule ligands that recruit KLHDC2 to the target protein, it will be able to specifically degrade proteins involved in cancer." (PMID 39887712, 2025).